PODXL (podocalyxin like)
Diseases named in the same sentence as PODXL in open-access papers (continued):
Sharing a sentence is not in itself a finding about the gene and the disease.
embryonal carcinoma (3 papers, 2013 to 2025). A non-seminomatous malignant germ cell tumor characterized by the presence of large germ cells with abundant cytoplasm resembling epithelial cells, geographic necrosis, high mitotic activity, and pseudoglandular and pseudopapillary structures formation. "In contrast, PODXL, a marker associated with atypical seminomas, showed markedly higher expression in both metastatic seminomas and embryonal carcinomas." (PMID 41203637, 2025). "Further in silico analysis of PODXL demonstrated high expression in both hESC and human embryonal carcinoma cell lines." (PMID 24146797, 2013).
esophageal adenocarcinoma (3 papers, 2016 to 2020). A malignant tumor with glandular differentiation arising predominantly from Barrett mucosa in the lower third of the esophagus. "Patients with resectable gastric or esophageal adenocarcinoma with high PODXL expression in their diagnostic biopsies have an excellent prognosis when treated with neoadjuvant ± adjuvant fluoropyrimidine- and oxaliplatin-based chemotherapy." (PMID 30355278, 2018). "In summary, patients with resectable gastric or esophageal adenocarcinoma with high PODXL expression in their diagnostic biopsies have an excellent prognosis when treated with neoadjuvant ± adjuvant fluoropyrimidine- and oxaliplatin-based chemotherapy." (PMID 30355278, 2018). "This is in contrast to our previous findings of PODXL being an independent prognostic biomarker for poor survival in gastric and esophageal adenocarcinoma treated with surgery up-front, thus suggesting a possible predictive role for PODXL." (PMID 30355278, 2018). "We have previously shown that podocalyxin-like protein (PODXL) is a prognostic biomarker for poor survival in gastric and esophageal adenocarcinoma treated with surgery up-front." (PMID 30355278, 2018). "We have previously shown that PODXL is an independent prognostic biomarker for poor survival in a cohort of resected gastric and esophageal adenocarcinomas treated with surgery up-front." (PMID 30355278, 2018). "And patients with gastric or esophageal adenocarcinoma would have a much better prognosis after treating with neoadjuvant ± adjuvant fluoropyrimidine– and oxaliplantin-based chemotherapy, if the expression level of PODXL is high." (PMID 32615943, 2020). "PODXL expression was similar in Barrett’s esophagus and gastric intestinal metaplasia (p = 0.671, data not shown)." (PMID 27478410, 2016). "The present study demonstrates a superior prognosis for patients with gastric or esophageal adenocarcinoma with high PODXL expression, treated with neoadjuvant ± adjuvant fluoropyrimidine- and oxaliplatin-based chemotherapy, compared to those with negative or low PODXL expression." (PMID 30355278, 2018).
glomerular disease (3 papers, 2022 to 2026). "We identified four novel truncating mutations in the PODXL gene found in four Spanish index cases affected by glomerular disease, which were considered likely pathogenic." (PMID 40282423, 2025). "As glomerular diseases progress, loss of the podocyte foot process is accompanied by loss of podocyte markers such as Podocalyxin (PODXL) and Synaptopodin (SYNPO)." (PMID 35883199, 2022). "In conclusion, we provide new evidence regarding the relevance of monoallelic LoF variants in the PODXL gene, highlighting the importance of exploring a new genetic disorder of podocytopathy, which needs to be included in glomerular disease panels and in human genetic disorder databases." (PMID 40282423, 2025).
lung carcinoma (3 papers, 2018 to 2021). "PODXL expression has been reported in several human cancers, including oral, breast, and lung cancer and leads to tumor growth, invasion, and metastasis." (PMID 29872738, 2018). "A role for PODXL in TGFβ-induced EMT has been reported in lung cancer metastases." (PMID 34201212, 2021). "PODXL is expressed in some types of human cancer tissues including oral, breast, and lung cancer tissues and may promote tumor growth, invasion, and metastasis." (PMID 29872738, 2018).
Nephropathy (3 papers, 2019 to 2025). A nonspecific term referring to disease or damage of the kidneys. "What’s more, two podocytes located downstream of miR-193 (i.e., WT1 and PODXL) were also nephropathy-relevant." (PMID 31352863, 2019).
oral cancers (3 papers, 2018 to 2020). "PODXL can be detected in normal tissues such as heart, breast, and pancreas as well as in cancers including lung, renal, breast, colorectal, and oral cancers." (PMID 30105309, 2018). "In previous studies, we also generated PODXL-knock out (PODXL-KO) cell lines using SAS OSCC cell lines, in order to investigate the function of PODXL in the proliferation of oral cancer cells." (PMID 30105309, 2018). "Targeting multiple targets, such as PODXL, EGFR, HER2, and PD-L1 may be needed for effective therapy to cure oral cancers." (PMID 32923698, 2020). "Targeting multiple targets, such as EGFR, HER2, PODXL, and CD44 may be needed for effective therapy to conquer oral cancers." (PMID 33000243, 2020).
pancreatic ductal adenocarcinoma (3 papers, 2013 to 2024). An infiltrating adenocarcinoma that arises from the epithelial cells of the pancreas. "PODXL has been found to be more frequently expressed (44 %) in pancreatic ductal adenocarcinoma as compared with other types of adenocarcinomas of the gastrointestinal and biliary tracts." (PMID 26028992, 2015).
renal failure (3 papers, 2020 to 2025). "Further, 24% of the 818 patients had a positive genetic finding associated with a genetic disorder, which explained renal failure; thus, 2% of positive cases were caused by PODXL-podocytopathy." (PMID 40282423, 2025). "PODXL-deficient mice have defective growth of podocyte foot processes, resulting in anuria and renal failure." (PMID 39844078, 2025). "Recently, heterozygous loss-of-function mutations in human PODXL were linked to late onset familial renal insufficiency in two distinct pedigrees from disparate ethnic backgrounds." (PMID 32523052, 2020).
atherosclerosis (2 papers, 2024 to 2025). A disease characterized by the build-up of fatty material and calcium deposition in the arterial wall resulting in partial or complete occlusion of the arterial lumen. "In our study, we identified APLNR, PCDH12, PODXL, SLC40A1, TM4SF18, and TNFRSF25 as the most relevant genes associated with lipid metabolism and atherosclerosis, highlighting their potential as diagnostic and immune markers." (PMID 40070840, 2025). "Through further differential analysis and screening using machine learning algorithms, APLNR, PCDH12, PODXL, SLC40A1, TM4SF18, and TNFRSF25 were identified as key diagnostic genes for atherosclerosis." (PMID 40070840, 2025). "We determined that APLNR, PCDH12, PODXL, SLC40A1, TM4SF18, and TNFRSF25 are key genes associated with lipid metabolism in samples affected by atherosclerosis." (PMID 40070840, 2025). "Our study employed various machine learning algorithms to identify that APLNR, PCDH12, PODXL, SLC40A1, TM4SF18, and TNFRSF25, among the lipid metabolism genes, can serve as diagnostic markers in patients with atherosclerosis and are associated with atherosclerotic immune infiltration." (PMID 40070840, 2025). "The ROC curve was employed to assess the predictive potential of these key gene markers in atherosclerosis, revealing that the AUC values for APLNR, PCDH12, PODXL, SLC40A1, TM4SF18, and TNFRSF25 were 0.763, 0.859, 0.780, 0.807, 0.792, and 0.848, respectively." (PMID 40070840, 2025). "Through our investigation, we discerned the crucial functions of APLNR, PCDH12, PODXL, SLC40A1, TM4SF18, and TNFRSF25 within the framework of atherosclerosis." (PMID 40070840, 2025).
B-cell lymphoma (2 papers, 2017 to 2021). "In mature B-cell non-Hodgkin lymphoma cells, PODXL overexpression leads to higher resistance to corticosteroid medication dexamethasone, reactive oxygen species, and immunotherapy monoclonal antibody drug obinutuzumab." (PMID 34201212, 2021).
breast tumor (2 papers, 2015 to 2017). "We previously showed that podocalyxin (gene name PODXL) is upregulated on a subset of primary breast tumors and is an independent predictor of progression, metastasis and poor outcome." (PMID 25887862, 2015).
diffuse large B-cell lymphoma (2 papers, 2017 to 2020). "Furthermore, elevated levels of PODXL expression were detected on Raji Burkitt lymphoma cell line and moderate levels on Karpas 422 diffuse large B-cell lymphoma cell line." (PMID 32046309, 2020). "By contrast, Ramos and Daudi Burkitt lymphoma, Pfeiffer diffuse large B-cell lymphoma, and Karpas 1718 splenic marginal zone lymphoma cell lines showed no expression of PODXL." (PMID 32046309, 2020).
focal segmental glomerulosclerosis (2 papers, 2023 to 2025). A renal disorder characterized by sclerotic lesions in the glomeruli. "Previous research has suggested that PODXL haploinsufficiency leads to podocytopathy with development of focal segmental glomerulosclerosis, a disorder that has been demonstrated in Podxl-deficient animal models and proposed as a primary cause in human families affected by this condition." (PMID 40282423, 2025).
glomerulosclerosis (2 papers, 2022 to 2025). A hardening of the kidney glomerulus caused by scarring of the blood vessels. "Moreover, decreased expression of WT1 can result in lower levels of nephrin and PODXL, which are linked to kidney diseases like glomerulosclerosis." (PMID 39844078, 2025).
liver cancer (2 papers, 2015 to 2025). An epithelial or non-epithelial malignant neoplasm that arises from the liver. "Our data demonstrated that EZR, CLIC5 and PODXL co-localization in the liver only occurs under the studied pathological conditions, suggesting that these proteins are potential biomarkers of liver cancer." (PMID 26135398, 2015). "Furthermore, another study proposed PODXL as a potential biomarker for the diagnosis of liver cancer." (PMID 41462970, 2025).
meningioma (2 papers, 2019 to 2021). A generally slow growing tumor attached to the dura mater. "PODXL upregulation is a cancer stem cell marker in meningiomas and a marker of poor outcome in patients with GBM." (PMID 33692826, 2021). "In the DCC low vs. DCC high expression groups, podocalyxin like (PODXL) was significantly upregulated in DCC low expression meningiomas in six of seven studies." (PMID 31083655, 2019). "The type I transmembrane protein podocalyxin like (PODXL) was markedly upregulated in DCC low expression meningiomas in six studies." (PMID 31083655, 2019). "Preliminary findings of a current project in our labs, wherein we are studying the immunofluorescene staining patterns of PODXL and other stem cell markers in cell cultures derived from progressive meningiomas, let us suggest that PODXL is expressed in these entities." (PMID 31083655, 2019). "Therefore, based on its association with tumor progression in a number of cancer types, assessment of PODXL for its functional implications in more aggressive meningiomas is envisaged." (PMID 31083655, 2019).
metastatic disease (2 papers, 2013 to 2023). "The findings in this study suggest that analysis of PODXL expression in the primary tumour is sufficient for its use as a prognostic and treatment predictive biomarker in CRC, also in patients with metastatic disease." (PMID 23819542, 2013).
nephrotic syndrome (2 papers, 2020 to 2023). A collection of symptoms that include severe edema, proteinuria, and hypoalbuminemia; it is indicative of renal dysfunction. "PODXL heterozygosity is associated with adult-onset kidney disease and podocalyxin shedding into the urine is a common biomarker of a variety nephrotic syndromes." (PMID 32523052, 2020).
pancreatic adenocarcinoma (2 papers, 2019 to 2020). "Their immunohistochemical analysis demonstrated the expression of PODXL-1 in 44% (71/160) of pancreatic adenocarcinomas, whereas none (0/18) of the intrahepatic and one (1/13) of the extrahepatic were stained." (PMID 30953499, 2019).
prostate tumors (2 papers, 2021 to 2023). "However, total GAL3, but not PODXL, levels in the prostate tumor showed an inverse association with the number of organs displaying macrometastases (r = −0.7681, P = 0.0744, n = 6 mice)." (PMID 36735782, 2023). "Using a weighted histoscore for intensity that accounts for regional differences within a tumor, both PODXL and GAL3 showed no clear pattern or directionality of change in total labeling between primary prostate tumors and metastases (n = 6 shRNA scramble control mice with PTs and metastasis)." (PMID 36735782, 2023).
rectal cancer (2 papers, 2013 to 2014). A primary or metastatic malignant neoplasm that affects the rectum. "In multivariable survival analyses adjusted for age, gender, Dukes classification, and differentiation grade, high PODXL expression remained significant for the whole CRC material as well as for the subgroups of rectal cancer and cancer of the LHC." (PMID 25004863, 2014). "Rectal cancer patients with high PODXL expression had significantly poorer DSS than did those with low expression (p = 0.009)." (PMID 25004863, 2014). "PODXL expression was also found to be mainly unaltered in pre- and post-irradiation surgically resected tumour specimens in rectal cancer patients (n=16)." (PMID 23819542, 2013). "Moreover, we have examined the potential effect of radiation therapy on PODXL expression in rectal cancer patients." (PMID 23819542, 2013).
renal carcinoma (2 papers, 2015 to 2022). A carcinoma arising from the epithelium of the renal parenchyma or the renal pelvis. "The function of CLIC5 is proposed to be similar to that of EBP50, which is responsible for the interaction between EZR and PODXL in renal carcinoma." (PMID 26135398, 2015). "In renal cancer, the interaction between EZR and PODXL occurs through EBP50, which serves as a scaffolding protein." (PMID 26135398, 2015).
serous ovarian carcinoma (2 papers, 2012 to 2021). "Likewise, overexpression of PODXL in serous ovarian cancer cell line OVCAR3 decreases adhesion and increases the formation of small cohesive nodules, where PODXL is localised to the apical surface." (PMID 34201212, 2021).
acute leukemia (1 paper, 2024). A clonal (malignant) hematopoietic disorder with an acute onset, affecting the bone marrow and the peripheral blood. "Therefore, considering the significant role of PODXL in the development of acute leukemia, invasion, and metastasis, the expression level of PODXL has been regarded as a diagnostic and prognostic factor." (PMID 38879474, 2024).
anaemia (1 paper, 2021). "During early development, PODXL is expressed on primitive murine erythroid cells (embryonic day 7–12), marking both circulating erythroblasts and their progenitors, while in adult mice, PODXL expression is restricted to erythroid progenitors during erythropoiesis stress conditions such as anaemia." (PMID 34201212, 2021).
anuria (1 paper, 2020). Absence of urine output. "Interestingly, some PODXL mutations manifest as anuria while others are associated with proteinuric kidney disease." (PMID 32523052, 2020).
Burkitt lymphoma (1 paper, 2020). A rare form of malignant mature B-cell non-Hodgkin lymphoma. "We have recently reported that forced expression of PODXL in Raji Burkitt lymphoma cells enhanced the formation of cytosolic lipid droplets." (PMID 32046309, 2020). "Our results indicate that PODXL promotes glutaminolysis and glutamine dependence but decreases glucose dependence in Raji Burkitt lymphoma cells." (PMID 32046309, 2020). "Recently, we have demonstrated that overexpression of PODXL in Raji Burkitt lymphoma cells increased migration towards CXCL12." (PMID 32046309, 2020). "We have recently demonstrated that overexpression of PODXL in Raji Burkitt lymphoma cells decreases dexamethasone- and hydrogen peroxide-induced cell apoptosis." (PMID 32046309, 2020). "In Raji Burkitt lymphoma cells, we showed that ectopic overexpression of PODXL enhanced cell proliferation and colony formation." (PMID 32046309, 2020). "In Burkitt lymphoma cells, PODXL has recently emerged as a molecule that promotes cell proliferation, survival, migration, resistance to chemo-immunotherapy, and metabolism reprogramming." (PMID 32046309, 2020). "Accordingly, we observed that Raji Burkitt lymphoma cells cultured in low-glucose conditions (0.5 mM) expressed increased surface levels of PODXL compared to those grown in high-glucose conditions (11 mM)." (PMID 32046309, 2020). "Recently, we have uncovered a new function for PODXL as a metabolic reprogramming inducer in Raji Burkitt lymphoma cells." (PMID 32046309, 2020). "We have recently shown that in the presence of 6-aminonicotinamide, a competitive inhibitor of G6PD and PPP, Raji Burkitt lymphoma cells overexpressing PODXL proliferated to a lesser extent than control cells, indicating that PODXL induces PPP flux, becoming dependent on this pathway." (PMID 32046309, 2020).
cervical cancer (1 paper, 2024). A primary or metastatic malignant neoplasm involving the cervix. "Podocalyxin-like protein (PODXL) is known to originate from tumor cells in several cancers; however, which cell type it is expressed in, whether and how it may contribute to tumor progression after radiotherapy or chemoradiotherapy in cervical cancer (CC) remain unknown." (PMID 39294825, 2024).
chronic hepatitis B (1 paper, 2025). "In the evaluation of histoscores obtained from immunohistochemical staining for PODXL, PTX3, and ISM1, a statistically significant difference was observed between liver tissues with fibrosis associated with chronic hepatitis B and those from the control group." (PMID 41462970, 2025). "In conclusion, in our study, we observed that the immunoreactivities of PODXL, PTX3, and ISM1 in liver tissue were increased in fibrotic livers associated with chronic hepatitis B, compared to liver tissues with normal or low-grade fibrosis." (PMID 41462970, 2025). "In our study, we observed significant PODXL immunoreactivity in liver tissue of patients with chronic hepatitis B. Importantly, we found a progressive increase in expression levels from low-grade to high-grade fibrosis." (PMID 41462970, 2025). "However, to date, the immunoreactivity of PODXL in liver tissue of individuals with chronic hepatitis B has not been systematically investigated." (PMID 41462970, 2025).
chronic lymphocytic leukemia (1 paper, 2020). "We found three- to eight-fold higher levels of PODXL expression in malignant cells compared to their normal B-cell counterparts in two out of five cases of follicular lymphoma and one out of three cases of chronic lymphocytic leukemia/small lymphocytic lymphoma." (PMID 32046309, 2020).
colorectal adenocarcinoma (1 paper, 2019). The most common type of colorectal carcinoma. "Of notice, in a xenograft mouse model of colorectal adenocarcinoma, a human-mouse chimeric anti-PODXL antibody was shown to inhibit tumor growth of PODXL expressing cancer cells." (PMID 31083655, 2019).
cystic kidney disease (1 paper, 2025). A congenital or acquired kidney disorder characterized by the presence of renal cysts. "Seven genes (3%) had no entries in OMIM (DLG5 in renal ciliopathies and cystic kidney diseases; and 6 in the proteinuric kidney diseases [APOE, DLC1, FAT1, ITSN1, PODXL and TNS2]) and were excluded." (PMID 40303230, 2025).
diabetic nephropathy (1 paper, 2019). "For another, patients with FSGS, minimal lesions, diabetic nephropathy, and IgA nephropathy were discovered with a reduction in the glomerular expression of PODXL." (PMID 31352863, 2019).
end-stage renal disease (1 paper, 2025). "Thus, complete deficiency of PODXL leads to severe congenital renal disease affecting critical processes of podocyte development, while its haploinsufficiency results in end-stage renal disease due to podocyte dysfunction." (PMID 40282423, 2025).